IRF1 (interferon regulatory factor 1)
Diseases named in the same sentence as IRF1 in open-access papers (continued):
Sharing a sentence is not in itself a finding about the gene and the disease.
glioma (17 papers, 2015 to 2025). A benign or malignant brain and spinal cord tumor that arises from glial cells (astrocytes, oligodendrocytes, ependymal cells). "Mechanistically, studies suggest that SP140 promotes PD-L1 expression through STAT1/IRF1 activation in tumor-associated macrophages, which may explain its association with immune escape and poor prognosis in cancers such as glioma and ccRCC." (PMID 41188771, 2025). "Our results showed that the expression of IRF1 was significantly increased in high‐grade gliomas, and the promoter methylation level of PD‐L1 was also significantly decreased." (PMID 37786553, 2023). "Previously, we have shown that STAT1/IRF-1 signaling was involved in the development of bevacizumab resistance (often mesenchymal), and that genetic inhibition of IRF1 increased apoptosis in bevacizumab-treated glioma cells." (PMID 34771447, 2021). "We found up-regulation of IRF1 expression concomitant with increased autophagy in bevacizumab-treated gliomas." (PMID 26362401, 2015). "Consistently, IRF1 depletion increased the efficacy of anti-VEGF therapy in a glioma xenograft model, which was due to less bevacizumab-promoted autophagy and increased apoptosis in tumors with down-regulated IRF1." (PMID 26362401, 2015). "Since IRF1 regulated autophagy in glioma cells in vitro, we then evaluated autophagy level in glioma xenograft tumor tissues." (PMID 26362401, 2015). "Our in vitro experiments on glioma cells showed that bevacizumab not only increased the expression level of IRF1, but also increased the size of IRF1, suggesting a possible posttranslational modification by bevacizumab treatment." (PMID 26362401, 2015). "Furthermore, BVZ-mediated autophagy is also dependent on interferon regulatory factor 1 (IRF1) expression in gliomas." (PMID 34178638, 2021). "Overall survival curves indicated that glioma patients with lower IRF1 (p = 4.42E-33), IRF2 (p = 2.22E-16), IRF3 (p = 1.43E-15), IRF4 (p = 0.004), IRF5 p = 5.84E-12), IRF7 (p = 6.85E-28), IRF8 (p = 0.001), and IRF9 (p = 0.000) transcript levels had significantly longer overall survival times." (PMID 33902005, 2021). "Among the 260 grade II, 267 grade III, and 173 grade IV glioma patients, significant correlations were observed between IRF1 (p = 8.00E-61), IRF2 (p = 6.80E-18), IRF3 (p = 1.70E-23), IRF5 (p = 2.30E-08), IRF7 (p = 1.90E-29), IRF8 (p = 0.029), IRF9 (p = 4.80E-05) expression and pathological grade." (PMID 33902005, 2021). "Taken together, these data indicate that IRF1-regulated autophagy might be one mechanism by which glioma tumors escape from the antiangiogenic therapy." (PMID 26362401, 2015). "We then generated stable glioma cell lines with specific down-regulation of IRF1." (PMID 26362401, 2015). "Interestingly, we found bevacizumab increased IRF1 expression in glioma tumors." (PMID 26362401, 2015). "IRF1 is a crucial regulator, the inflammation-driven activity of IRF1 and NF-κB promotes the reactivation of endogenous retrovirus K in motor cortical neurons of amyotrophic lateral sclerosis, and may play a role in the resistance of glioma to immune checkpoint blockade." (PMID 38383423, 2024). "Of these, IRF1, IRF2, and PRDM1 were upregulated in all grades of glioma, while CEBPB was just upregulated in grade III and combined." (PMID 33948562, 2021). "We found that IRF1, IRF2, IRF5, IRF8 and IRF9 were significantly upregulated in glioma compared to normal brain tissue." (PMID 33902005, 2021). "In summary, this study showed that IRF1, IRF2, IRF5, IRF8, and IRF9 mRNA levels were increased in glioma compared to normal tissue." (PMID 33902005, 2021). "We found that 4 of 26 predicted TFs (IRF1, IRF2, CEBPB, and PRDM1) were upregulated at the mRNA level in MR1 high gliomas." (PMID 33948562, 2021).
glioma (continued). "We found that IRF1, IRF2, IRF5, IRF7, IRF8, and IRF9 were upregulated in glioma compared with normal tissue." (PMID 33902005, 2021). "Our findings demonstrate that bevacizumab-mediated autophagy was decreased in IRF1 down-regulation tumors, which was coincident with increased apoptosis, and an improvement in efficacy of anti-VEGF therapy in glioma xenografts." (PMID 26362401, 2015). "Gene chip analysis of control and bevacizumab resistant glioma tumors also showed up-regulation of STAT1-IRF1 pathway (2.6 fold and 2.91 fold up-regulation for STAT1 and IRF1, respectively)." (PMID 26362401, 2015). "Down regulation of IRF1 by shRNA blocked autophagy and increased AIF-dependent apoptosis in bevacizumab-treated glioma cells." (PMID 26362401, 2015). "Collectively, these results indicate that IRF family members, including IRF1, IRF2, IRF5, IRF8 and IRF9, may serve as prognostic biomarkers and indicators of immune status in glioma patients." (PMID 33902005, 2021). "Of these, IRF1 (low grade n = 4, high grade n = 4), IRF2 (low grade n = 8, high grade n = 16), and CEBPB (low grade n = 2, high grade n = 7) also showed different and disperse levels of staining in histology (non-detected; +, low; ++, medium; +++, high) from THPA among high- and low-grade gliomas." (PMID 33948562, 2021). "Moreover, the expression of Cd274 was well correlated with the respective expression of Ifng, Irf1, Gbp5, and Ccl2, demonstrating that selected IFN-γ-induced genes serve as feasible substitute indicators for IFN-γ level and thus might synergistically indicate the prognosis of glioma." (PMID 30333036, 2018).
autoimmune disease (16 papers, 2013 to 2025). A disorder resulting from loss of function or tissue destruction of an organ or multiple organs, arising from humoral or cellular immune responses of the individual to their own tissue constituents. "We identified that a genetic variant associated to autoimmune diseases also affects the expression of the nearby transcription factor IRF1 gene in early immune response, followed by expression change of other genes in late immune response." (PMID 34314424, 2021). "This is a plausible molecular mechanism for the inflammatory bowel disease association in this locus, with genetic predisposition for overactivation of IRF1 immune response (by the rs17622517 C allele) possibly contributing to autoimmune disease risk." (PMID 34314424, 2021). "We found evidence that this autoimmune disease -associated variant is located in a genomic regulatory element that responds to immune stimulus and affects expression of IRF1 and a complex gene regulatory network." (PMID 34314424, 2021). "IRF5 has also gained some attention in recent years for its involvement in autoinflammatory and autoimmune diseases, and much like IRF1, it has been implicated in induced cell death." (PMID 34685580, 2021). "HLA-mediated inflammatory reactions is thought to be linked with CD, HCV and other autoimmune disorders whereby a number of HLAs in this study were mainly regulated by IRF1 and VDR." (PMID 29379596, 2017). "On the other hand, IRF1 (which may be affected by an autoimmune disease risk variant in monocytes) was strongly induced by LPS to a similar extent in MDM in all individuals." (PMID 38421405, 2024). "IRF1 gene expression was also indicated to associate with autoimmune disease risk." (PMID 38474381, 2024). "An autoimmune disease risk variant: A master regulatory effect via IRF1 under immune stimulation?" (PMID 34314424, 2021). "The tight interaction with the IRF1/survivin or survivin/SMAD3 complexes maintains expression of IFN-sensitive genes that are clinically relevant in several autoimmune diseases, including RA,48,64 systemic lupus erythematosus, and Sjögren’s syndrome." (PMID 36425763, 2022). "Although this is a likely mechanism for IRF1’s role in autoimmune disease, further in vitro and/or in vivo experiments would be required to elucidate this disease mechanism and is a potential topic to be explored in future research." (PMID 34314424, 2021). "In mice, IRF1 was shown to promote the severity and incidence of autoimmune diseases like collagen-induced arthritis (CIA) and experimental allergic encephalomyelitis." (PMID 30515152, 2018). "One SNP (rs2070721) in IRF1 and SNPs (rs2297518 and rs4795067) in NOS2 are also associated with autoimmune diseases, such as multiple sclerosis (MS) in Italy, AS in Europe, and psoriasis in Pakistan." (PMID 27965977, 2016). "Members of the Interferon Response Factor family of transcriptional regulators, IRF1 and IRF8, have been identified as genetic risk factors for several chronic inflammatory and autoimmune diseases." (PMID 24954358, 2014). "Also, CCR7+/RELB+/IRF1+ T cells had been revealed as an independent responsor in JIA among other types of autoimmune diseases, severing as potential therapeutic target." (PMID 40406113, 2025). "It remains to be determined how dectin-1 signaling renders IRF1 transcriptionally inept and this could be used for therapeutic intervention in autoimmune diseases that are characterized by enhanced type I IFN responses." (PMID 36456734, 2022). "In this study, we first mapped trans-eQTLs in a data set of primary monocytes stimulated with LPS, and discovered that a risk variant for autoimmune disease, rs17622517 in an intron of C5ORF56, affects the expression of the transcription factor IRF1 20 kb away." (PMID 34314424, 2021).
autoimmune disease (continued). "The miR-19a-3p/STAT1/IRF1 axis may be a potential target in macrophage polarization, and highlights a better comprehension for potential mechanism of pathogenesis and progression of diseases such as chronic inflammatory and autoimmune diseases." (PMID 34017248, 2021). "Additionally, the specific mechanistic link between the transcriptional IRF1 response described here and autoimmune disease is unknown." (PMID 34314424, 2021). "Indeed, hyper-activation of IRFs (most notably IRF1, IRF3, IRF5, IRF7, and IRF9) has been implicated in disease pathogenesis as it leads to unrestricted production of IFNs, which is linked to the development of numerous inflammatory and autoimmune diseases." (PMID 30515152, 2018). "Across the T cell populations of these autoimmune diseases, CCR7, RELB, and IRF1 were notably highly expressed in JIA T cells, which revealed that CCR7+/RELB+/IRF1+ T cells independently response for JIA." (PMID 40406113, 2025). "However, the multiple functions of IRF-1 imply that IRF-1 may be suitable as a selective gene with an engineered delivery system for biotherapies of various types of cancer and autoimmune diseases." (PMID 23420765, 2013).
atherosclerosis (15 papers, 2016 to 2025). A disease characterized by the build-up of fatty material and calcium deposition in the arterial wall resulting in partial or complete occlusion of the arterial lumen. "For example, silencing IRF1 alleviated atherosclerosis in ApoEKO mice by regulating lipid metabolism and foam cell formation and highly suggests that IRF1 activation is a risk factor for the occurrence and development of atherosclerosis." (PMID 39840103, 2024). "IRF1 expression is downregulated by estradiol and reported for being associated with fibrinogen levels, which is a known risk factor for atherosclerosis in carotid arteries." (PMID 32469969, 2020). "Unsupervised DEGs analysis of SMCs revealed increased expression in Abcb8ECKO of TGF-β-pathway genes such as Tgfb1, Tgfb2, Tgfb3, Mmp2 and Col1a1, inflammatory genes such as Ccl2 (encoding for MCP1) and Csf1 as well as atherosclerosis-associated genes including Egr1, Sqstm1, Irf1, Sox4 and Xylt1." (PMID 41252867, 2025). "It is noteworthy that the protective role of IRF1 deficiency in atherosclerosis is multifactorial, and cell type-selective genetic manipulation should be taken into account in our future studies to elaborate on cell specific effects of IRF1 in pro-atherosclerotic mice." (PMID 31367250, 2019). "Additionally, IRF-1 activation is a risk factor for atherosclerosis." (PMID 40223932, 2025). "However, IRF1 deficiency attenuated the effects of LPS on the aggravation of atherosclerosis." (PMID 31367250, 2019). "We also demonstrate the role of the TLR master regulon Sub1, and its downstream effect on the transcription factor Irf1, in promoting proinflammatory M1 polarization and atherosclerosis." (PMID 34378353, 2021). "Further we examined the expression of IRF1 in atherosclerosis- prone ApoE-/- mice and normal C57BL/6 mice." (PMID 31367250, 2019). "Our current data demonstrate that LPS, which cooperates with ox-LDL and induces IRF1 activation, exacerbates the pathogenesis of atherosclerosis in ApoE-/- mice." (PMID 31367250, 2019). "Collectively, these data suggest that LPS exacerbates the development and progression of atherosclerosis in ApoE-/- mice, and these effects are dependent, at least partly, on IRF1 activation." (PMID 31367250, 2019). "Our study aims to explore the role of IRF1 in atherosclerotic foam cell formation and understand the functional diversity of IRF1 in various cell types contributing to atherosclerosis." (PMID 31367250, 2019). "In particular, STAT1, 2 and 3; IRF1 and 8 have recently been recognized as prominent modulators of inflammation, especially in immune and vascular cells during atherosclerosis." (PMID 27166190, 2016). "Oil red staining demonstrated a significant increase in lipid in vascular plaques in high-fat-fed mice, and AAV-sh-IRF-1 could alleviate the symptoms of atherosclerosis." (PMID 33424012, 2020). "In general, our research demonstrated that IRF-1 and CCL19 are involved in the course of atherosclerosis, which may be used as diagnostic markers and new therapeutic targets." (PMID 33424012, 2020). "Importantly, silencing IRF-1 inhibited atherosclerosis in high-fat-fed mice, inhibited the proliferation and migration of VSMCS, and down-regulated the expression of CCL19." (PMID 33424012, 2020). "Despite significant pathological implication of low-grade inflammation in foam cell formation and atherosclerosis 13-15, whether IRF1 is involved in this process also remains elusive." (PMID 31367250, 2019). "It provides an impetus for further exploration of the role of endothelial IRF1 in atherosclerosis." (PMID 31367250, 2019). "To determine whether IRF1 responds to the progression of atherosclerosis, we detected its levels in macrophages from early- and late-stage lesions respectively." (PMID 31367250, 2019). "Consistently, ChIP assays demonstrated increased interaction between IRF1 and the TTK promoter during postinjury neointimal formation and atherosclerosis." (PMID 39716891, 2025).
atherosclerosis (continued). "Interferon regulatory factor-1 (IRF1) plays an important role in regulating immunity, inflammation, and apoptosis in atherosclerosis." (PMID 35406663, 2022). "Interferon regulatory factor 1 (IRF-1) contributes to the pathological phenotype of VSMCs during atherosclerosis by increasing CCL19 transcription, whereas silencing IRF-1 inhibits angiotensin proliferation and migration and downregulates CCL19 expression, thereby suppressing atherosclerosis." (PMID 36720935, 2023). "Although a strong positive correlation of IRF1 with oxidized low-density lipoprotein (ox-LDL) in mammalian atherosclerotic lesions has been suggested previously 12, little information is available concerning the effects of IRF1 on foam cell formation and atherosclerosis." (PMID 31367250, 2019).
cervical carcinoma (15 papers, 2010 to 2024). A carcinoma arising from either the exocervical squamous epithelium or the endocervical glandular epithelium. "Activation of the STAT3/IRF1 pathway increases the susceptibility of cervical cancer cells to chemical treatments." (PMID 38789431, 2024). "These variants are highly expressed in cervical cancer tissue and associated with attenuated IRF-1 transcriptional activity." (PMID 29599126, 2018). "In addition, IRF1 expression is associated with response to radio/chemotherapy in cervical cancer patients." (PMID 32326356, 2020). "We found that IRF-1 over-expression remarkably suppressed the expression of PI3K/mTOR signalling pathway-related proteins in cervical cancer cells." (PMID 33076322, 2020). "Given the fact that IRF1 is a STAT3-inducible mediator for cell death enhancement in cervical cancer cells, it will be interesting to investigate the role of STAT3 and ERp57 in IRF1-depedent surface CRT exposure in the future." (PMID 32326356, 2020). "STAT1/IRF-1 pathways initiated by IFNγ had been shown to be important in TNFα and IFNγ synergism in inducing cervical cancer cell apoptosis." (PMID 27342639, 2016). "A previous study demonstrated that IRF1 is a mediator for interferon-γ-induced inhibition of hTERT expression and telomerase activity in cervical cancer cells." (PMID 20842112, 2010). "For example, rearrangements of chromosome 5, especially 5p gain, are often related to cervical cancer, and a miRNA located at 5p13.3, miR-579, is predicted to target the genes PTGS2 and IRF1, which are involved in cervical cancer." (PMID 20567512, 2010). "Another recent case suggests that the PI3KCA-E545K mutation enhances PD-L1 expression by upregulating PD-L1 transcription factor interferon regulatory factor 1 and that the PIK3CA mutation may be a biomarker for pembrolizumab treatment in cervical cancer." (PMID 38215117, 2024). "PI3KCA-E545K mutation enhances PD-L1 expression by upregulating PD-L1 transcription factor interferon regulatory factor 1 and that the PIK3CA mutation could be a biomarker for PD-1 blockade treatment in cervical cancer." (PMID 38215117, 2024). "The low expression of IRF1 in cervical cancer may contribute to the decreased levels of miR-203 by blocking the transcription of miR-203." (PMID 25658920, 2015). "Our study establishes a linear signaling pathway from IRF1 to BANF1 that may contribute to BANF1-induced tumorigenesis in cervical cancer." (PMID 25658920, 2015). "Thus, alternative splicing affecting exons 7, 8, and 9 may be another critical mechanism negatively regulating IRF-1 in cervical cancer." (PMID 29599126, 2018). "We found that among the molecules demonstrating correlation, excluding IRF-1 and TFRC, expression in cervical cancer was negatively correlated with hsa_circ_0000276 expression, and expression of the key genes was positively correlated with one another." (PMID 36894874, 2023). "To elucidate how E6 and its binding protein, IRF-1, affect the PI3K/AKT pathway in cervical cancer cells, we investigated the role of PDK1, Akt, mTOR, and 4E-BP1, which are downstream signalling regulators of PI3K." (PMID 33076322, 2020). "CaSki cervical cancer cells were transfected with control, HPV16 E6, IRF-1 or IRF-1 plus HPV16 E6, respectively." (PMID 33076322, 2020). "Other forms of IRF1, lacking exons 7, 8, 9, and their combinations, were identified in cervical cancer tissue samples (IRF1Δ7, IRF1Δ8, IRF1Δ9, and others)." (PMID 38396830, 2024). "These genes were uploaded to the GEPIA database, which showed that in cervical cancer and paracancerous tissues, the expression levels of seven genes, CD47, FKBP4, IRF-1, LDHA, PDIA3, TFRC, and SLC16A1, were significantly higher in cancer tissues (p < 0.05) than in healthy tissues." (PMID 36894874, 2023). "IRF1 isoforms without exons 7, 8, 9, and their combinations were found in cervical cancer." (PMID 38396830, 2024).